TGFBR2 (transforming growth factor beta receptor 2)
Diseases named in the same sentence as TGFBR2 in open-access papers (continued):
Sharing a sentence is not in itself a finding about the gene and the disease.
cancer (continued). "For example, TGFβ–BMP signalling was mostly inactivated by co-SMAD SMAD4 mutations in MSS cancers, but by one or more indel receptor mutations (TGFBR2, ACVR2A, BMPR2 and ACVR1B) in MSI cancers." (PMID 39112709, 2024). "Immunohistochemical analysis of clinical tissue samples revealed that TGFBR2 expression was significantly lower in LUAD cancer tissues compared to controls." (PMID 39364312, 2024). "In a recent study, it was discovered that USP11 has the ability to enhance the stability of TGFβ receptor type 2 (TGFBR2) and initiate downstream TGFβ signaling in cancer cells." (PMID 39420007, 2024). "Reciprocally, silencing of TGFBRII in Detox-iCAF prevented the transition from Detox-iCAF to ECM-myCAF in the presence of cancer cells, confirming that TGFBR2 is necessary for this transition." (PMID 38561380, 2024). "Further, we discovered that loss of TGFBR2, frequently mutated in NPC and other types of human cancers, not only promoted the progression of NPC in mice, but also the lung metastasis." (PMID 39049720, 2024). "The first group of genes was well-known cancer-related genes, i.e., Fgfr2, Hras, Tgfbr2, Nf1, and Erbb2." (PMID 37063417, 2023). "The newly identified genes included several well-known cancer drivers, such as Fgfr2, Hras, Tgfbr2, Nf1, and Erbb2, as well as others whose function in cancer remains elusive." (PMID 37063417, 2023). "Tgfbr2 KO on cancer cells promotes TME remodeling and immune exclusion; Socs1 KO made the tumors more responsive to PD-L1 blockade." (PMID 36313703, 2022). "One of the members of the TGF-β/Smad signaling pathway is transforming growth factor-beta receptor type II (TGFBR2) that acts as a cancer suppressor." (PMID 35715800, 2022). "Taken together, it can be argued that MIR4435-2HG can promote cancer progression by targeting the miR-1224-5p/TGFBR2 axis." (PMID 35715800, 2022). "Mechanistic investigation showed that ALG3 promoted radioresistance and cancer stemness by inducing glycosylation of TGF-β receptor II (TGFBR2)." (PMID 33931075, 2021). "Cancer stemness is enhanced by miR-21-5p, which is capable of targeting TGFBR2 in colorectal cancer." (PMID 33799952, 2021). "Mechanistically, our results further revealed ALG3 promoted radioresistance and cancer stemness by inducing glycosylation of TGF-β receptor II (TGFBR2)." (PMID 33931075, 2021). "The evidence proved that ADAMTS9-AS1 restrained invasion and proliferation of cancer cells through sequestering miR-301b-3p to target TGFBR2 and regulate JAK STAT signaling pathway." (PMID 34900984, 2021). "The disruption of Tgfbr2 signaling in cancer cells resulted in increased chemokine signals SDF-1/CXCR4 and CXCL5/CXCR2 that enhanced MDSC infiltration into tumors, which led to the promotion of tumor invasion and metastasis." (PMID 34356885, 2021). "As we have mentioned, miR-655 is an EMT-inhibiting miRNA targeting ZEB1 and TGFBR2 at the same time in cancers." (PMID 33902589, 2021). "The TGFBR2 promoter exhibited hypermethylation not only in the transition from dysplasia to cancer, but also from normal epithelium to cancer." (PMID 32046777, 2020). "Many upregulated genes such as cancer stem cell marker (SOX2/9), hypoxia inducible factor (HIF1α), TGF-β signaling associated receptor (TGFBR2), and differentiation related transcription factor (RUNX2) were reported to promote tamoxifen resistance." (PMID 32420379, 2020). "Cancer cells with treatment of DNA methyltransferase inhibitor 5-Aza-2′-deoxycytidine reversed methylation levels in the TGFBR2 promoter and induced cell cycle arrest." (PMID 32046777, 2020). "Given these problems, there has therefore been increasing pre-clinical interest in developing TGFβ and TGFBR2 inhibitors for prostate and other cancers." (PMID 31428571, 2019).
cancer (continued). "The remaining 28 ‘cancer’ genes identified as upregulated and hypomethylated, as with the acute RE analysis, this included those implicated in TGF-beta signalling (TGFB3, TGFBR2, LEF1 and MECOM) after chronic RE in human skeletal muscle." (PMID 30862794, 2019). "A study elucidated miR-301b to be a member of the pan-cancer oncogenic miRNA superfamily, which targets TGFBR2." (PMID 31113460, 2019). "TGFBR2 expression was shown to decrease with cancer progression, which can partly explain the resistance of RCC cells to the TGF-β1 growth-inhibiting effect." (PMID 31842336, 2019). "The shared variants included mutations in key genes of intestinal carcinogenesis (e.g., APC K562fs, V782fs, and Q205X), well-known cancer driver mutations (KRAS G12D), and recurrent homopolymer deletions characteristic of MSI tumors (e.g., TGFBR2 K153fs)." (PMID 31779681, 2019). "These lines were derived using CRISPR to remove Tgfbr2 from the primary mouse cancer cell line (BMFA3), which was obtained from a KPfC animal." (PMID 31609088, 2019). "In Pten;Tgfbr2 tumors, the invasive cancer was highly proliferative and was largely Krt5-high and Krt8-low, whereas fewer cells stained positive for Ki67 in intact HGPIN ducts that were luminal." (PMID 29782499, 2018). "As with many mouse models of human cancer, one potential confounding issue is the complete inactivation of a particular gene (Tgfbr2 in this case)." (PMID 29782499, 2018). "These cells were extremely rare in HGPIN in Pten;Tgfbr2 tumors, but were slightly increased in the invasive cancer." (PMID 29782499, 2018). "In this context, it is worth noting that in the extensively basal Pten;Tgfbr2 null invasive tumors from the PbCre4 model, there is enrichment for gene expression signatures that are indicative of aggressive luminal cancers." (PMID 29782499, 2018). "We have further shown that restoration of TGFβRII in Tgfbr2 cKO SCC reduced the frequency of these CD34+ CSCs, demonstrating that loss of TGFβ signaling is a requirement for CSC maintenance in transition zone carcinoma." (PMID 28219480, 2017). "IHC assays revealed that TGFBR2 was primarily expressed in cancer tissues instead of normal tissues and exhibited a cytoplasmic distribution." (PMID 27120811, 2016). "In particular, SKI and PRKCZ in 1p36.33 have been reported to contribute to the loss function of TGFBR2 and SMAD4 in cancer." (PMID 26374103, 2015). "The reduction or loss of TGFBR2 expression enables cancer cells to escape the growth inhibitory effect of TGF-β and to gain a proliferative advantage, and the downregulation of TGFBR2 is a frequent event in early-stage CRC." (PMID 26061281, 2015). "The TGFBR2 gene encodes a receptor for the TGF-β pathway and is a known cancer driver gene in MSI-positive CRC." (PMID 24308539, 2013). "For example, a single copy of the TGFBR2 transgene is integrated into the MSI cancer cell line genome." (PMID 23468914, 2013). "Our findings strongly suggest that the TGF-b-induced EMT can be suppressed by miR-655, independently of miR-200 family members, through translational inhibition of ZEB1 and TGFBR2 in cancer cells." (PMID 23690952, 2013). "Our results suggest the potential of the EMT-suppressor miR-655 targeting ZEB1 and TGFBR2 as a prognostic marker and therapeutic agent for cancer." (PMID 23690952, 2013). "TGFBR2 is particularly interesting because the expression of TGFBR2 has been shown to be lost progressively during malignant progression of diverse types of cancer." (PMID 22912877, 2012). "For example, TGFBR2 is potentially suppressed by aberrant expression of miR-20a in cancer and by induction of miR-21 during adipogenic differentiation." (PMID 21401928, 2011). "On the other hand, the most frequently down regulated AM genes are TGFBR2 (7/13 of cancer models), BAG3, CLU, LGALS1, LTBR, SGK (in 6/13)." (PMID 19402918, 2009). "Moreover, TGFBR2 (SE = 1.6) was expressed dominantly in endothelia, and other stromal cells, but weakly in cancer cells." (PMID 40075643, 2025).
cancer (continued). "While the specific role of miR-34b in regulating the TGFBR2 gene in brain injury remains unclear, extensive studies on miR-34b in cancer and other diseases provide valuable insights." (PMID 39129166, 2025). "Furthermore, pan-cancer bioinformatics analysis revealed a strong association between the six-gene ITL signature and both mesenchymal signatures and TGFBR2 expression in a variety of systemic cancers." (PMID 40277917, 2025). "Importantly, previous work has demonstrated a high correlation between protein and RNA data for TGFBR1 and TGFBR2 within the same cell line (Spearman’s correlation: 0.672 for TGFBR1, 0.771 for TGFBR2), based on comprehensive data from 375 cancer cell lines." (PMID 38753874, 2024). "Finally, the mechanism of TGFBR2 in regulating the phosphorylation of STAT1 to suppress BC cancer development should be validated." (PMID 39525474, 2024). "Since pericytes were mainly found in BM tumors, they may have widespread interactions of TGFβ-TGFBR2 with various types of cells to regulate cancer vascularization via increased expression of SLUG." (PMID 36671569, 2023). "Compared with other mesenchymal stem cells, the most highly expressed oncogene and tumor suppressor genes in WJ-MSCs are PDGFRA and TGFBR2, which may be related to their strong anti-cancer properties." (PMID 36011369, 2022). "Overexpression of PEG10 and TGFBR2 in MSCs would help to shed light on their effect on cell proliferation and whether this effect is cancer-specific." (PMID 35739280, 2022). "Importantly, both attenuation of glycosylation using tunicamycin and inhibition of TGFBR2 using LY2109761 differentially abrogated the stimulatory effect of ALG3 overexpression on cancer stemness and radioresistance." (PMID 33931075, 2021). "In addition, rescued expression of Tgfbr2 in Six1−/− MCA205 cancer cells restored collagen VI gene expression." (PMID 34782761, 2021). "Collectively, these meta-analyses suggest that in a given tissue, aggregated expression of FN1, TGFBR2, TGFB2, and TGFBI might serve as an index for the extent of cancer-associated fibroblasts (CAFs)." (PMID 32605311, 2020). "TGFBR2, a direct target of Hsa-mir-204, has recently emerged as a target for cancer therapy." (PMID 32775417, 2020). "In later cancer stages, TGFBR2 even functions to promote epithelial–mesenchymal transition (EMT)." (PMID 33138184, 2020). "At the genetic level, for instance, the TGFBR2 protein was truncated and inactivated because of TGFBR2 mutations, thus inhibiting its growth regulatory functions in microsatellite instability-high (MSI-H) cancers." (PMID 30935128, 2019). "Based on the observation of upregulated EMT and associated key signature genes such as TGFB2, TGFBR2, SMAD2, and ZEB1 in the high-risk patients, we infer that m6A regulatory machinery must interact with EMT to regulate cancer metastasis in various human malignancies." (PMID 31069256, 2019). "However, in the Pten;Tgfbr2 tumors, a large proportion of the invasive cancer consisted of cells that were strongly positive for Krt5, with Krt8 cells intermixed." (PMID 29782499, 2018). "The most striking difference was the high proliferation rate of basal cells in invasive cancer in the Pten;Tgfbr2 tumors compared to those in the Pten or in intact HGPIN ducts in the same animals, consistent with a preferential effect of TGFß signaling on basal cell proliferation." (PMID 29782499, 2018).
cancer (continued). "Restoration of Tgfbr2 in Tgfbr2 cKO CD34+ SCCs dramatically reduced the frequency of mCherry+CD34+ CSCs from 6.5% to 2.5%, demonstrating that loss of TGFβ signaling is a requirement for CSC maintenance in transition zone carcinoma." (PMID 28219480, 2017). "Also, treatment with DHT in A2780 cancer cell line resulted in a decrease in mRNA levels and in TGFBR2 protein levels, consistent with studies in other ovarian cell lines." (PMID 26091707, 2016). "However, other latent mechanisms require further exploration for the clarification of the specific functions of TGFBR2 in carcinogenesis and cancer progression." (PMID 27120811, 2016). "Similar increase in TGFBR2 expression was seen in the cancer spheres, compared to parental cells." (PMID 25011053, 2015). "The mechanism of TGFBR2 deregulation varies in different types of cancer." (PMID 26061281, 2015). "TGFBR2 encodes a receptor for the TGF-β pathway and is a known cancer driver gene." (PMID 24782526, 2014). "The role of TGFBR2 in oncogenesis has been investigated in several cancer types." (PMID 24606633, 2014). "MSI cancers commonly have mutant TGFBR2 which may negate the proliferative effects of the TGF-beta pathway and impair the epithelial to mesenchymal transition in MSI compared to MSS cancers." (PMID 23110075, 2012). "TGFBR2 is a major TGF-β signaling molecule often found to be one of the genes altered in cancer." (PMID 22912877, 2012). "Mutations in the MSI target genes IGF2R and BAX were found in one (33.3%) and two (66.7%) out of the three rectal MSI-H carcinomas, respectively, whereas no mutations were detected in TGFBR2, MSH3, and MSH6 microsatellite sequences in this test series." (PMID 20979647, 2010). "Thus, we hypothesize that TGFβ released by various types of cells within TME may interact with TGFBR2 in abundant pericytes within BM tumors to modulate cancer angiogenesis." (PMID 36671569, 2023). "In addition, String pathway interaction analysis identified six proteins (TGFBR2, TGFA, FGF21, SMAD4, TGFBR1, and FZD3) that were at the intersection of the cancer-associated pathways and, importantly, which were restored to their younger crosstalks by the rounds of TPE." (PMID 35999337, 2022). "Therefore, we speculated that ADAMTS9-AS1 mediated TGFBR2 levels via sequestering miR-301b-3p, thus regulating cancer proliferation and invasion." (PMID 34900984, 2021). "The M1 frameshift neoantigen derived from TGFBR2, the first described cMS driver mutation in MSI cancer and also the first ever frameshift neoantigen characterized for its immunological properties in MSI cancer in pioneering studies, displays the highest IRS (28.57%)." (PMID 32958755, 2020). "Many studies have demonstrated that the expression of TGFBR2 is modulated by MREs and their miRNAs in various cell types, such as miR-145 in vascular smooth muscle cells, miR-9-5p in hepatic stellate cells, miR-9 and miR-9-5p fibroblasts (HCFs), miR-520e, miR-9-5p, and miR-135b in cancer cells." (PMID 30935128, 2019). "Two significantly enriched pathways in LUAD and their related DEmRNAs, namely transcriptional misregulation in cancer (TGFBR2, FLI1, ERG and SIX1) and central carbon metabolism (NTRK3 and SLC7A5), were speculated to play key roles in LUAD regulated by DEmiRNAs." (PMID 30761256, 2019).
cancer (continued). "However, in cancer tissues, TGFBR2 seems negatively related to hTERT, (r = −0.12, P = 0.13)." (PMID 28195144, 2017). "Therefore, the modulation of TGFBR2 by miR-135b may explain why the upregulation of miR-135b during CRC carcinogenesis promotes cancer progression." (PMID 26061281, 2015). "However, the mechanism by which cancer cells downregulate TGFBR2 is unclear." (PMID 26061281, 2015). "Therefore, our observation suggests that TGFBR2 expression level may be a critical factor to determine the fate of the role of TGF-β in cancer cells." (PMID 23457527, 2013). "Furthermore, cancers that do not demonstrate mutations in any TGFβ1 signaling cascade members, show down-regulated levels of TGFBR2, demonstrating the oncogenic potential of TGFβ1 pathway." (PMID 23951322, 2013). "TGFBR2 is the cognate receptor for TGF-β, a well-established inducer of EMT in cancers, in the canonical TGF-β/SMAD signaling pathway." (PMID 39844333, 2025). "The augmented expression of TGFBR2, CDC25A, SMAD7, and RELA and downregulation of p27 are major events in cell proliferation and cancer invasion." (PMID 40761498, 2025). "The increased expression of TGFBR2, CDC25A, SMAD7, and RELA and downregulation of p27 are major events in cell proliferation and cancer invasion." (PMID 40755497, 2025). "TGFBR2 is deubiquitinated by USP11 to maintain the TGF-β signal pathway and the glycosylation of TGFBR2 enhances the radio-resistance and BC cell stemness; therefore, maintaining a normal TGF-β pathway is essential for cancer cell control." (PMID 39525474, 2024). "TGFB2 was included in a four gene signature (FN1, TGFB2, TGFBR2, and TGFBI), as an indicator of CAF abundance, which predicted survival in TCGA pan-cancer cohort comprising 9356 patients from 32 cancer subtypes." (PMID 37296997, 2023). "Many of these genes were transcription factors and several of them were known cancer genes (e.g., APC, BCL2, ERBB2, HRAS, TGFBR2)." (PMID 35008420, 2022). "Such pathologies accumulate and lead to somatic mutations, including reading frame alterations in genes, such as APC, TGFBR2 or BAX, which results in an accelerated process of polyp-to-cancer transformation in large polyps." (PMID 36553592, 2022). "TGFBR2, a key member of the TGF-β pathway, is frequently deleted during carcinogenesis in many types of cancers, including NSCLC." (PMID 34996416, 2022). "Reportedly, miR-655 is an EMT-inhibiting miRNA that targets TGFBR2 and ZEB1 at the same time in cancers." (PMID 33902589, 2021). "Increased H3K9 acetylation was observed on the promoter of Transforming Growth Factor Beta Receptor 2 (TGFBR2) after the activation of SNAI1/2, leading to transcription of TGF-β, a major player in the regulation of cancer metastasis." (PMID 33803458, 2021). "Alteration of TGFBR2, which functions in the same signaling pathway as SMAD4, was also restricted to the cancer in one case." (PMID 32796935, 2020). "Transforming growth factor beta receptor type II (TGFBR2), as the members of the TGF-β/Smad pathway, is a cancer suppressor." (PMID 28195144, 2017). "The biological effects of TGFBR2 and STAT3 have been extensively studied in cancer and the immune system." (PMID 26972162, 2016). "The combined 208 cases yielded no additional high-frequency mutated genes, however, multiple lower frequency (<2.5% recurrence) cancer-related genes were identified including ATM, ARID2, TGFBR2 and ACVR1B." (PMID 25855536, 2015). "Known cancer genes included focal amplifications of MYC (8q24.21), KRAS (12p12.1) and AKT2 (19q13.2), and homozygous deletions of TGFBR2 (3p24.1) and CDKN2A (9p21.3)." (PMID 18535672, 2008). "We observed a trend for higher fibroblast TGFβ signature (F-TBRS36) in partially and epigenetically escaped samples, and that TGFβ receptor 2 (TGFBR2) had significantly higher expression in escaped cancer biopsies than nonescaped or partially escaped ones." (PMID 41193656, 2025). "Numerous cancer cell lines had imbalanced expression levels of TGFBR1 and TGFBR2." (PMID 38753874, 2024).